GZMB (granzyme B)
Diseases named in the same sentence as GZMB in open-access papers (continued):
Sharing a sentence is not in itself a finding about the gene and the disease.
IgG4-related disease (1 paper, 2025). "Given that TFR cells have been implicated in suppressing GZMK+ cytotoxic TFH cells in ectopic lymphoid follicles of patients with IgG4-related disease, we assessed the ratio of GZMK+TIA-1+ or GZMB+TIA-1+ TFK cells to TFR cells." (PMID 41030456, 2025).
inactive (1 paper, 2019). "The percentages of granzyme B+ CD56bright NK cells were higher in SLE patients with active disease compared to those in controls (75.7 ± 5.9% vs. 53.1 ± 4.7%, p = 0.002) and to SLE patients with inactive disease (75.7 ± 5.9% vs. 59.3 ± 6.2%, p = 0.024), respectively." (PMID 31049024, 2019).
intestinal infection (1 paper, 2024). "Since IEL are the major cell type expressing GzmA and GzmB constitutively in the mouse, we could use GzmA/B dKO to address the function of IEL-derived Gzms in intestinal infection." (PMID 39137883, 2024).
iron deficiency (1 paper, 2024). "Diet-induced iron deficiency resulted in increased viral loads and decreased GzmB+ NK cells, whereas iron supplementation clearly improved the NK cell cytotoxicity and increased the mitochondrial polarization." (PMID 39877355, 2024). "Collectively, iron deficiency increased viral replication and decreased GzmB in NK cells implicating a primary role of iron for immune activation rather than in FV replication." (PMID 39877355, 2024).
Kawasaki disease (1 paper, 2020). A rare inflammatory disease characterized by an acute febrile, systemic, self-limiting, medium-vessel vasculitis primarily affecting children. "IL-35 also inhibited tumor necrosis factor-α and granzyme B secretion by CD14+ monocytes from patients with Kawasaki disease, however, only granzyme B was responsible for the cytotoxicity of CD14+ monocytes." (PMID 32276581, 2020). "On the other hand, IL-35 dampened TNF-α and granzyme B production by CD14+ monocytes in Kawasaki disease, however, only granzyme B contributed to the cytotoxicity of CD14+ monocytes." (PMID 32276581, 2020). "Elevated circulating IL-35 played an important immunosuppressive role to CD14+ monocytes function in Kawasaki disease, including direct cell-to-cell contact-mediated naïve CD4+ T cells activation/differentiation and granzyme B-induced cytolytic function." (PMID 32276581, 2020).
Marfan syndrome (1 paper, 2013). A disorder of the connective tissue. "Although filamin A can be cleaved by caspase activity as well as granzyme B, proteomics analysis showed no alterations in activity of either caspase or granzyme B in the aortic media of Marfan syndrome patients." (PMID 23977256, 2013).
medullary breast carcinoma (1 paper, 2020). An infiltrating breast carcinoma with a relatively favorable prognosis. "In the Curtis dataset, the expression of GZMB was 5.918 times higher in medullary breast carcinoma tissue than normal tissue." (PMID 33042828, 2020).
Miscarriage (1 paper, 2022). A pregnancy that ends at a stage in which the fetus is incapable of surviving on its own, defined as the spontaneous loss of a fetus before the 22th week of pregnancy. "In a previous study, we observed elevated levels of cytotoxic granules and inflammatory cytokines, such as IL‐2 and IL‐12, as well as of perforin and granzyme B, at the implantation site rather than at the systemic level in a murine miscarriage model induced by α‐galactosylceramide (α‐GalCer)." (PMID 35444491, 2022).
myelodysplastic syndrome (1 paper, 2019). A clonal hematopoietic disorder characterized by dysplasia and ineffective hematopoiesis in one or more of the hematopoietic cell lines. "Nevertheless, our data confirm previous observations of GzmB expression in MDSCs in patients suffering from myelodysplastic syndrome." (PMID 31212684, 2019).
myelofibrosis (1 paper, 2021). A partial or complete replacement of the bone marrow stroma by fibrous tissue. "Internal consistency analysis regarding evaluation of the immunohistochemical markers yielded good or excellent results for myelofibrosis, nestin niches, CD34-positive blast counts, and counting of granzyme B, T-bet, FoxP3, CD3, CD4, CD8, and E-cadherin positive cells." (PMID 33704530, 2021).
myeloid malignancies (1 paper, 2011). "The data herein show that the donor G/G or A/G allele, which represents mutant granzyme B, is associated with a significantly improved overall survival (OS) and reduced transplant-related mortality (TRM) in patients with myeloid malignancies." (PMID 21886827, 2011). "The effects of the granzyme B G/G or A/G genotype on the reduced TRM in patients with myeloid malignancies might be a consequence of increased resistance to infections in these recipients." (PMID 21886827, 2011).
myxoma (1 paper, 2024). A benign soft tissue neoplasm characterized by the presence of spindle and stellate cells, lobulated growth pattern, and myxoid stroma formation. "Lymphocytes within myxoma tissues exhibit elevated expression of certain genes associated with extracellular matrix adhesion, while their capacity to express cytotoxic molecules such as GNLY, GZMB, and NKG7 is diminished." (PMID 39090109, 2024). "The mIHC experiments revealed that compared to normal tissue, myxoma exhibited a higher proportion of CD8 + T cells expressing TOX and higher expression levels of GZMK while showing lower expression levels of GZMB, which confirmed the characteristic dysfunction of CD8 + T cells in myxoma." (PMID 39090109, 2024).
narcolepsy (1 paper, 2023). A sleep disorder characterized by a tendency for excessive sleepiness during the day which occurs even after adequate sleep in the nighttime. "Moreover, testing whether some genes or pathways, such as the perforin/granzyme B pathway, are directly involved in narcolepsy pathogenesis will require further studies." (PMID 38077397, 2023).
nasopharyngeal carcinoma (1 paper, 2023). A carcinoma arising from the nasopharyngeal epithelium. "A recent study found that alterations in the Granzyme B gene (GZMB/H) negatively predicted ICB efficacy in nasopharyngeal cancer patients." (PMID 37607911, 2023).
NK / T-cell lymphoma (1 paper, 2021). "Indeed, the final histological diagnosis required in all cases, including ours, the immunohistochemistry analisys specific for the Extranodal NK / T-cell lymphoma: cells positive for granzyme B, CD3, CD45RO, and CD56, and negative for CD20 and ALK1." (PMID 34160395, 2021).
non-Hodgkin lymphoma (1 paper, 2021). Distinct from Hodgkin lymphoma both morphologically and biologically, non-Hodgkin lymphoma (NHL) is characterized by the absence of Reed-Sternberg cells, can occur at any age, and usually presents as a localized or generalized lymphadenopathy associated with fever and weight loss. "Natural killer/T-cell lymphoma (NKTCL) is a highly invasive subtype of non-Hodgkin lymphoma, typically positive for cytoplasmic CD3, CD56, cytotoxic markers, including granzyme B and TIA1, and Epstein-Barr virus (EBV)." (PMID 33628584, 2021).
obstructive sleep apnea (1 paper, 2023). "CD40LG and GZMB might play a vital role in the visceral adipose tissue homeostasis of obstructive sleep apnea patients." (PMID 36923793, 2023).
olfactory neuroblastoma (1 paper, 2024). An olfactory neuroblastoma arising in the paranasal sinus. "However, when looking at activated, Granzyme B+, NK cells, these were found in higher abundance in samples where patients went on to have post-treatment recurrences and in patients who passed due to their olfactory neuroblastoma P = 0.0221 and P = 0.048, respectively)." (PMID 38822345, 2024).
Opportunistic infection (1 paper, 2012). An infection that is caused by a pathogen that would generally not be able to cause an infection in a host with a normal immune system. "In the lobules, perforin- and granzyme B-positive cells in the ACR group were significantly more than those in the biliary complication and opportunistic infection groups, while TIA-1-positive cells was significantly fewer than those in non-ACR groups." (PMID 23111143, 2012).
osteoarthritis (1 paper, 2019). A noninflammatory degenerative joint disease occurring chiefly in older persons, characterized by degeneration of the articular cartilage, hypertrophy of bone at the margins and changes in the synovial membrane. "Among them, subgroup SC-T5 expressed a high level of granzyme B and was present at the same level in patients with RA and osteoarthritis, a non-inflammatory disease, suggesting that they may be associated with a non-inflammatory state." (PMID 31681279, 2019).
pancreatic ductal adenocarcinoma (1 paper, 2019). An infiltrating adenocarcinoma that arises from the epithelial cells of the pancreas. "Since γδ T cells utilize TNF-related apoptosis inducing ligand (TRAIL) for killing of tumor cells in addition to granzyme B and perforin, we investigated the role of the TRAIL-/TRAIL-R system in γδ T cell-cytotoxicity toward pancreatic ductal adenocarcinoma (PDAC) and other cancer cells." (PMID 31555275, 2019).
Pancytopenia (1 paper, 2021). An abnormal reduction in numbers of all blood cell types (red blood cells, white blood cells, and platelets). "Then, haematopoietic stem/progenitor cells are attacked by activated CD8+ T lymphocytes through the Fas/FasL pathway, perforin, granzyme B, and TNF-β, causing serious pancytopenia." (PMID 37600601, 2021).
penile squamous cell carcinoma (1 paper, 2024). "Furthermore, elevated levels of granzyme B were linked to more favorable outcomes in individuals diagnosed with penile squamous cell carcinoma according to the literature." (PMID 39596210, 2024).
periodontitis (1 paper, 2023). An acute or chronic inflammatory process that affects the tissues that surround and support the teeth. "The machine-learning method, RF, was performed to create an ideal model to predict the occurrence of periodontitis and selected five hub PRGs (CHMP2B, GZMB, ZBP1, IL1B, and IRF1)." (PMID 37090158, 2023).
pharyngitis (1 paper, 2022). Inflammation of the throat most often caused by viral and bacterial infections. "To further elucidate functional immune responses during acute S. pyogenes pharyngitis, we analysed cells for CD69 expression (a marker of activation), CXCR3 (a marker of migration) and intracellular perforin and granzyme-B expression (cytotoxic proteins involved in cell lysis)." (PMID 35140232, 2022).
plasma cell dyscrasia (1 paper, 2017). "Lenalidomide also enhanced the antigen-specific secretion of Granzyme B in HDs (p = 0.028) and patients with plasma cell dyscrasia (PD) (p ≤ 0.001)." (PMID 29228683, 2017).
proliferative diabetic retinopathy (1 paper, 2022). Advanced retinopathy due to diabetes mellitus characterized by the formation of new vessels in the retina. "Then, we further analyzed the differentially expressed genes between active FVMs and inactive FVMs according to the same thresholds and found an upregulated gene GZMB, indicating that GZMB may play an important regulatory role in different states of proliferative diabetic retinopathy." (PMID 35957838, 2022).
Retinal atrophy (1 paper, 2024). A nonspecific term denoting wasting, especially as a result of degeneration, of the retinal pigment epithelium (RPE) and neurosensory retinal cells. "However, in the GzmB-deficient mice, a less robust decrease in both waveforms was present and remained non-significant, suggesting an exacerbation of retinal atrophy and functional loss associated with the accumulation of extracellular GzmB in WT mice." (PMID 38498232, 2024).
Rotavirus infection (1 paper, 2025). Infection with any of the rotaviruses. "Similarly, there were more frequencies of intraepithelial IFN-γ-expressing CD4+ T cells and Granzyme B-expressing CD4+ T cells in small intestines from Trim29IEC-KO suckling mice than those from Trim29fl/fl mice after rotavirus infection for 3 days." (PMID 39396665, 2025).
Salmonella Infections (1 paper, 2024). Infections with bacteria of the genus SALMONELLA. "Surprisingly, GzmB KO mice were significantly protected against Salmonella infection, with no systemic bacteria found in many of the mice 5 days post infection, and no weight loss." (PMID 39137883, 2024).
scrub typhus (1 paper, 2022). Scrub typhus is a rare dust mite-borne infectious disease caused by the Orientia tsutsugamushi bacterium and characterized clinically by an eruptive fever which is potentially serious. "It is known that CD44+ activated T cells may contribute to controlling bacterial growth through production of cytokines (e.g. IFN-γ and TNF-α) and granules (granzyme B), and that decreased CD4+ T cell numbers observed in acute scrub typhus patients is likely due to increased cell apoptosis." (PMID 35479068, 2022).
septic peritonitis (1 paper, 2017). Septic peritonitis is an inflammatory condition of the peritoneum that occurs secondary to microbial contamination. "In the present study, we report the intracellular expression of gzmA and gzmB and their function in a mouse model that resembles the clinical condition commonly associated with septic peritonitis by E. coli." (PMID 28694562, 2017). "To get insight into the influence of gzmA and gzmB deficiency on the local inflammatory response elicited during septic peritonitis, we measured proinflammatory (TNF-α, IFN-γ, and IL-1β, IL-6) and anti-inflammatory (IL-10) cytokines as well as MCP-1 and KC levels in PLF." (PMID 28694562, 2017).
skin infection (1 paper, 2019). An inflammatory process affecting the skin, caused by bacteria, viruses, parasites, or fungi. "Following VacV-GP33 skin infection, memory P14 CD8+ T cells that initially trafficked into the skin expressed granzyme B, as did memory cells undergoing proliferation in the draining lymph node." (PMID 30875408, 2019).
soft tissue sarcoma (1 paper, 2022). A malignant neoplasm arising from muscle tissue, adipose tissue, blood vessels, fibrous tissue, or other supportive tissues excluding the bones. "This fact was demonstrated when CD8+ CD69+ TILs expanded from patients with soft tissue sarcoma had more tumor-specific functional capacity due to more IFN-γ and granzyme B production." (PMID 36513720, 2022).
Susac syndrome (1 paper, 2022). Susac syndrome (SS) is a rare disorder characterized by the triad of central nervous system (CNS) dysfunction, branch retinal artery occlusions (BRAOs) and sensorineural hearing loss (SNHL). "Intervention with GzmB significantly improved disease progression in the mouse model of Susac syndrome." (PMID 36439094, 2022).
systemic vasculitis (1 paper, 2021). "By contrast, both CD4+ and CD8+ T-cells were proliferating in the affected skin, with both containing cytotoxic granzyme B. In addition, our data have demonstrated that plasma sPD-L1 was positively correlated with CRP levels in patients with systemic vasculitis." (PMID 34625602, 2021).
T-cell neoplasms (1 paper, 2020). "From the immunohistochemical results, decreased MAX expression correlated with the expression of cytotoxic molecules such as TIA-1 and granzyme B. Recent reports have shown that expression of cytotoxic molecules may be independent prognostic factors in mature T-cell neoplasms including ALCL21–23." (PMID 32587329, 2020).
thrombotic disorders (1 paper, 2020). "In particular, disease-specific upregulation of SERPINE1 (encoding plasminogen activator inhibitor-1; PAI-1), VWF (von Willebrand factor), and GZMB (Granzyme B) gene expression levels in COVID19 + ICU patients may contribute to thrombotic disorders in COVID19 patients." (PMID 33306162, 2020).
tongue tumors (1 paper, 2019). "The immune correlates for the protective efficacy of α-PD-1 therapy in the tongue tumors included a higher frequency of CD8+ T cells, specifically those with cytotoxic potential as evidenced by expression of Granzyme B (CTL)." (PMID 31533840, 2019).
toxoplasmosis (1 paper, 2025). A parasitic disease contracted by the ingestion or fetal transmission of toxoplasma gondii. "The enhanced T cell responses with IFN-γ and Granzyme B elicited by the multi-antigen approach further support the strategic advantage of combinatorial antigen formulations in toxoplasmosis vaccine development." (PMID 41321568, 2025).
tubulointerstitial nephritis (1 paper, 2022). "Based on the in vitro studies, it may be conceivable that PTECs cross-present antigens in immune-mediated GN thereby promoting cytotoxic CD8+ T cells, which may induce apoptotic cell death in the tubular system, e.g., by release of GzmB, which thereby promotes tubulointerstitial nephritis." (PMID 35563816, 2022).
uterine tumor (1 paper, 2024). "While T cells were the most abundant immune cells in all three samples, the NK cells within the uterine tumor had proportionally higher expression of perforin and granzyme B." (PMID 39076998, 2024).
uveitis (1 paper, 2023). An inflammatory process affecting a part of or the entire uvea. "In contrast, BD uveitis showed a selective clonal expansion of effector memory CD8+ T cells expressing cytotoxic molecules such as GZMB." (PMID 37720629, 2023). "In contrast, uveitis in the BD patient had few of these effector CD4+ T cells but was characterised by clonally expanded effector CD8+ T cells expressing CCL5, GZMA, GZMB and PRF1." (PMID 37720629, 2023).
viral hepatitis (1 paper, 2017). An acute or chronic inflammation of the liver parenchyma caused by viruses. "Cytotoxic proteins were only expressed in a small fraction of liver CD69 + CD8+ T cells in patients without viral hepatitis, however, in livers from CHB patients more CD69 + CD8+ T cells were granzyme B+." (PMID 28733665, 2017).
viral pneumonia (1 paper, 2022). Inflammation of the lung parenchyma that is caused by a viral infection. "These cells produce the viral pneumonia marker GZMB, which can cleave the BV01 peptide sequence in tissue sections from mice with viral pneumonia and, by proxy, in vivo to produce a reporter signal that is detectable in urine." (PMID 35696579, 2022).
vulvar cancer (1 paper, 2017). "These nests were more intensely infiltrated only by CD8+ cells, therefore, granzyme B-dependent elimination of tumor cells seems to be major action of CD8+ cells rather than CD56+ in vulvar cancer surveillance." (PMID 28515351, 2017).